TNF (tumor necrosis factor)
Diseases named in the same sentence as TNF in open-access papers (continued):
Sharing a sentence is not in itself a finding about the gene and the disease.
uveitis (continued). "All four TNF-α antagonists have been proven to be equally effective in controlling the spinal manifestations of AS and uveitis; however, infliximab and adalimumab have been shown to be slightly more effective for the treatment of extra-spinal features of the disease including acute uveitis." (PMID 34394873, 2021). "Elevated levels of TNFα have been detected in the eyes and serum of patients affected by uveitis." (PMID 33671954, 2021). "Although the exact etiology remains unknown, TNF-α is regarded as a critical cytokine in the development of uveitis, including VKH." (PMID 35096888, 2021). "This study provides evidence that tocilizumab might be a useful adjunctive therapeutic option for children with uveitis refractory to anti-TNF treatments." (PMID 32280950, 2020). "Finally, we compared the incidence of uveitis between the total period under TNF treatment, considering all therapeutic lines, and between the date of diagnosis and introduction of the first TNFi." (PMID 32336278, 2020). "Lastly, being a soluble receptor, etanercept might be able to extend the half-life of intraocular TNF-α stimulating uveitis until the receptor-ligand complex is removed from the eye." (PMID 32337619, 2020). "A PubMed literature search was performed using the following terms: ophthalmic complication, uveitis, inflammatory eye disease, optic neuritis, neuropathy, adverse events, anti-TNF, TNF alpha inhibitor, infliximab, etanercept, adalimumab, golimumab, certolizumab, and biologics." (PMID 32337619, 2020). "In addition to these demographic and clinical factors, etanercept, a common TNF inhibitor treatment for JIA, has been considered as a potential risk factor in the development of uveitis in a cohort of patients with RA." (PMID 31605484, 2020). "Meta-analyses have shown the inferiority of etanercept over other anti-TNF-α agents in uveitis." (PMID 33171664, 2020). "Under these circumstances, many of the ocular adverse events reported on this review may be regarded as a paradoxical effect of anti-TNF therapy, particularly uveitis." (PMID 32337619, 2020). "Anti-TNFα agents are effective in reducing uveitis recurrences by 50% to 80% according to studies." (PMID 32231384, 2020). "In a retrospective study with JIA-related uveitis patients, all achieved complete control of uveitis within 5 months of first infusion over a mean follow up of 44 months, demonstrating the long-term efficacy of rituximab for anti-TNF-α refractory cases." (PMID 32508634, 2020). "In the database of spontaneously reported uveitis under anti-TNF therapy in the USA, TNF-α soluble receptor (namely etanercept) was found to be associated with the majority of cases compared to monoclonal antibodies (43 with etanercept, 14 with infliximab, and 2 with adalimumab)." (PMID 32337619, 2020). "In particular, anti-TNF-α monoclonal antibodies elicit a highly suppressive effect on ocular inflammatory attacks and have proven to be effective in the treatment of uveitis related to BS by improving visual acuity, showing a good long-term drug retention rate and a steroid-sparing effect." (PMID 32508524, 2020). "Although awareness of potential treatment side effects should be highlighted, it remains to be seen whether the suggested link between TNF inhibitors and the onset of uveitis is substantiated by more quality data." (PMID 32337619, 2020). "TNF-α and IL-6 are important proinflammatory cytokines that mediate the pathogenesis of uveitis." (PMID 33510636, 2020). "All patients, including those with chronic uveitis, had -238GG and -308GG genotype, which suggests that in TIN patients the studied genetic variation in TNF-α does not have any influence on uveitis risk." (PMID 30779760, 2019). "Promising results for anti-TNF alpha treatment in paediatric uveitis were available in case series." (PMID 31367810, 2019).
uveitis (continued). "It is recommended in the EULAR consensus that anti-TNF alpha could be considered as first line therapy in cases with severe sight-threatening BD-related uveitis." (PMID 31367810, 2019). "The aim of this review made by a group of ophthalmologists and rheumatologists with recent and fruitful experience regarding the anti-TNF treatment of uveitis in patients with SpA is to make the community of ophthalmologists aware of this biologic therapy and that it is the right time to use it." (PMID 30206554, 2018). "One important molecule involved in uveitis that is modulated by TNF-α is MMP-9." (PMID 29302691, 2018). "It is worth noting that resident microglia migrated toward the photoreceptor cell layer before circulating macrophages and polymorphonuclear cells in experimental uveitis, which could generate numerous neurotoxic agents, such as TNF-α and NO." (PMID 29686615, 2018). "In a total of 3512 patients the use of any of these drugs in the year before uveitis onset significantly reduced the risk for uveitis, and the use of MTX within the first year of disease and of the combination of MTX with a TNF-α inhibitor had the highest protective effect." (PMID 29996864, 2018). "Furthermore, MMP secretion and activation were found to be induced and modulated by TNF-α and interleukin (IL)-1α during uveitis." (PMID 29686615, 2018). "TNF-α levels are high in the aqueous humor and serum of patients with Behcet's disease, as well as in the aqueous humor and serum of rats with endotoxin-induced uveitis (EIU)." (PMID 28751819, 2017). "Therefore, it is possible that TNF-α produced by choroidal mast cells and infiltrating macrophages has an important role in the pathogenesis of uveitis." (PMID 28751819, 2017). "It is well known that TNF-α plays a primary role in uveitis." (PMID 28751819, 2017). "TNF is present at high concentrations in both aqueous humor and serum of patients with uveitis, and may participate actively in the pathogenesis of uveitis." (PMID 25888248, 2015). "This meta-analysis of patient-level data from 8 RCTs significantly advances the notion that anti-TNF therapy may be a credible alternative for AS patients with uveitis." (PMID 25888248, 2015). "Anti–TNF therapy was preventive for flares or new onset of uveitis in AS patients, and might be an alternative for these patients." (PMID 25888248, 2015). "In addition, dexamethasone has been reported to down-regulate pro-inflammatory cytokines like INF-γ and TNF, while up-regulating the levels of IL-10 in peripheral blood mononuclear cells from uveitis patients." (PMID 26700298, 2015). "Aqueous humour and sera of patients with uveitis present high TNF-α levels." (PMID 26270662, 2015). "Anti-TNF therapy has been shown to be beneficial for the treatment of uveitis in patients with AS." (PMID 25888248, 2015). "Furthermore, it has been reported that vitreous concentrations of IL-1, IL-6, and TNF-α were increased in an experimental uveitis rat model." (PMID 25679504, 2015). "Similar to the result of percent detectable, the vitreous levels of IFN-γ and sCD40L were significantly higher in uveitis group than in PDR group, whereas those of IL-4, IL-17A, IL-22, IL-31, and TNFα were significantly higher in PDR group compared with uveitis group." (PMID 26352837, 2015). "TNF-α has also been reported to play a role in the pathogenesis of ocular inflammation, with high levels detected in the serum and aqueous humor of patients with uveitis." (PMID 24886032, 2014). "Still, uveitis is a manifestation of SpA: assuming uveitis is an adverse event triggered by anti-TNFα inhibitors might be an awkward statement." (PMID 24991219, 2014). "This should be kept in mind when evaluating patients with uveitis, particularly in those patients for whom TNF inhibitor therapy is being considered, as these agents may worsen demyelinating disease." (PMID 24891944, 2014).
uveitis (continued). "There is an ongoing debate whether uveitis during anti-TNFα has to be considered as paradoxical effect or an inadequate response to therapy." (PMID 24991219, 2014). "Similarly, another anti-TNFα therapy, infliximab, reduces IL-17A in ocular fluid from uveitis patients with Behcet’s disease." (PMID 24823369, 2014). "Uveitis can occur long time after the start of anti-TNFα therapy, usually after 12–27 months." (PMID 24991219, 2014). "Cytokines play a critical role in the pathogenesis of uveitis and we therefore investigated whether the different genotypes of rs2488457 affected production cytokines such as TNF-α, IL-1β, IL-6, IL-8, MCP-1, IFN-γ, IL-10 and IL-17." (PMID 24816862, 2014). "Likewise, increased levels of TNF have been detected in serum and/or aqueous humor of uveitis patients when compared with controls." (PMID 23983404, 2013). "However, treatment with TNF-α inhibitors indicated a dramatic anti-inflammatory effect against major BD lesions, particularly for uveitis." (PMID 24049437, 2013). "In conclusion, our experience with adalimumab has been positive, leading to the control of both arthritis and uveitis in a child with psoriatic JIA complicated by uveitis, which was resistant to previous treatments with NSAIDs, DMARDs, and initial TNF inhibitor therapy etanercept." (PMID 24191219, 2013). "Thus, intravitreal injection of TNF in rabbits and Lewis rats has shown to induce the development of uveitis." (PMID 23983404, 2013). "The purpose of this study was to determine whether anti-tumour necrosis factor alpha (anti-TNF-α) antibody, infliximab, can inhibit T helper 17 (Th17) differentiation in uveitis patients who have Behçet's disease (BD)." (PMID 22546542, 2012). "However, compared to proinflammatory eye disease such as experimental uveitis induced by lipopolysaccharide, the level of TNF-α is much lower in our model." (PMID 22802951, 2012). "We next confirmed that recombinant TNF-α could promote Th17 induction in BD patients who have active uveitis." (PMID 22546542, 2012). "Serious adverse events or side effects were not significant, so that adalimumab can be considered a potential treatment option in JIA-associated uveitis, even in patients nonresponsive to previous other anti-TNF therapy." (PMID 21180427, 2010). "In addition to the standard use in rheumatic diseases, TNF inhibitory drugs have also shown to be effective in preventing experimental uveitis." (PMID 21180427, 2010). "Hence, elevation of cAMP can be a therapeutic strategy to overcome endothelial barrier dysfunction in response to TNF-α during corneal transplantation failure and/or uveitis." (PMID 20824160, 2010). "Anti-TNF-α agents are increasingly proving to be effective in the control of uveitis." (PMID 20029145, 2010). "Furthermore, etanercept has been shown to be less effective than other monoclonal TNF inhibitors in controlling uveitis, which may limit its applicability in assessing the impact of TNF inhibitor spacing on uveitis recurrence." (PMID 41007651, 2025). "For patients with uveitis experiencing suboptimal therapeutic response to adalimumab dosed every two weeks, therapeutic drug monitoring and neutralizing drug antibody detection may help clinicians optimize TNF-alpha inhibitor treatment." (PMID 39936006, 2025). "In this context, HTLV-1-infected CD4 T-cells collected from patients suffering from uveitis, which is the second-most frequent HTLV-1-associated disease in Japan after HAM-TSP, also produce large amounts of various inflammatory cytokines such as IL-1, IL-6, TNF-α, and IFN-γ." (PMID 41020241, 2025). "Notably, concomitant uveitis may favor TNF-α inhibitors, whereas JAK inhibitors are promising options after failure of conventional therapy." (PMID 41341579, 2025). "However, the available data on the impact of tapering adalimumab (or TNF inhibitors) on uveitis recurrence in AS patients is scarce, and its effects remain unclear." (PMID 41007651, 2025).
uveitis (continued). "However, TNF -alpha inhibitors such as adalimumab and infliximab are contraindicated in patients with MS, and the number of other immunosuppressive options that benefit both MS and uveitis are more limited." (PMID 41239063, 2025). "TNFα is known to play a crucial role in the pathogenesis of AS, as it is over-produced in AS predominantly by active macrophages and T-lymphocytes, playing key roles in the inflammation of spine and sacroiliac joints and extra-articular manifestations including uveitis." (PMID 38337605, 2024). "Additionally, elevated inflammatory cytokine levels, such as TNF-α and IL-6 in the aqueous humor of uveitis patients, may contribute to myopia progression." (PMID 39006849, 2024). "The anti-tumor necrosis factor (anti-TNF) agents such as infliximab, etanercept and adalimumab, used as an alternative or in combination with synthetic disease-modifying antirheumatic drugs (DMARDs) in the treatment of juvenile idiopathic arthritis (JIA) and JIA-associated uveitis." (PMID 37848930, 2023). "However, a recent phase-2 study reported poor effectiveness of the subcutaneous administration for the treatment of patients with anti-TNF refractory JIA-associated uveitis since its primary outcome on treatment response was not completely met." (PMID 37700264, 2023). "However, few publications exist on the use of TNF-α inhibitors in children with uveitis." (PMID 36831165, 2023). "In these studies, well-being after anti-TNF therapy improved more compared to the current study, although patients were older, had higher disease activity and could have had systemic arthritis or a history of uveitis." (PMID 36376976, 2022). "For instance, it has been shown that there is an intra-day variation of TNF-α in healthy patients throughout the day, with increased levels in the morning and late in the day, although it is unclear if these results could be the same in uveitis patients." (PMID 36498608, 2022). "Third, AS-uveitis complex is most frequently observed as anterior uveitis and responds well to topical corticosteroids, whereas posterior uveitis is usually refractory to topical treatments and frequently requires treatments with systemic corticosteroids and anti-TNF agents to reduce recurrences." (PMID 35087531, 2021). "Likewise, management decisions regarding patients with uveitis are influenced by the risk of precipitating or exacerbating episodes of demyelination, e.g., following anti–tumor necrosis factor biologic therapy, and other neurologic complications of immunosuppressive treatments for uveitis." (PMID 33127747, 2021). "Patients in their series had similar uveitis etiologies and also received a varied combination of treatment regimens, including a combination of local corticosteroid injections or dexamethasone implants, systemic corticosteroids, antimetabolites and anti-TNF alpha agents." (PMID 33718975, 2021). "All the other anti-TNF-α monoclonals such as Golimumab and Fab ́-fragment conjugated with polyethylene glycol agents, such as Certolizumab-pegol, have been reported to have a certain effect on uveitis, albeit the power of those studies limits the judgement of such reports as anecdotal at the moment." (PMID 33634341, 2021). "The effects of IL-6 in uveitis may be further augmented by ambient intraocular TNF-α and IL-1β." (PMID 34285659, 2021). "We know that the uveitis in some patients may still flare despite anti-TNF therapy." (PMID 30886955, 2018). "In summary, the present study demonstrates that low dose of LPS pretreatment could prevent subsequent endotoxin-induced uveitis by reducing the expression of TNF-α in the aqueous humor, and this protective effect of endotoxin tolerance is associated with PI3K/AKT pathway." (PMID 28804726, 2017).
uveitis (continued). "Compared to those with no DMARD treatment in the year before uveitis onset, the risk of uveitis was significantly decreased by methotrexate (hazard ratio [HR] 0.63, p = 0.022), by TNF inhibitors (HR 0.56, p = 0.001) and by a combination of the two (HR 0.10, p = 0.001)." (PMID 27121190, 2016). "Previous studies showed that TNF-α antagonist could also suppress uveitis in human and mice." (PMID 25653480, 2015). "Anti-TNF therapy including ETA could be a credible alternative for AS patients who have uveitis." (PMID 25888248, 2015). "Uveitis during TNFα inhibitors could be regarded as a paradoxical effect." (PMID 24991219, 2014). "However, successfully treated uveitis is described with all anti-TNFα therapies." (PMID 24991219, 2014). "Uveitis during TNFα inhibitors could rather be the sign of an insufficient control of the disease." (PMID 24991219, 2014). "Due to the refractory course of uveitis to previous DMARD treatment, Group 1 received Adalimumab (24 mg/sq mt, every 2 weeks), as first anti-TNFα choice; Group 2 received Adalimumab, as second anti-TNFα drug, due to the loss of efficacy of Infliximab, administered after a period of at least 1 year." (PMID 23587261, 2013). "Intravitreal injection of TNF-α in rabbits and in rats induces acute uveitis characterized by an increase in flare (aqueous humor protein) and a polymorphonuclear infiltrate in the anterior chamber, suggesting that TNF-α may be an initiating factor in the pathogenesis of uveitis." (PMID 22389806, 2012). "Thus, suppression of effector T-cell differentiation by anti-TNF-α therapy may protect uveitis patients from severe ocular inflammation." (PMID 22546542, 2012). "The high TNF-α levels observed in the serum of our IU patients are in accord with earlier findings of high expression of TNF-α by peripheral blood CD4+ lymphocytes in patients with active uveitis of different origins, in active Behçet disease and in presumed ocular sarcoidosis." (PMID 21850175, 2011). "Cytokines, including IL-6, TNF-α, IFN-γ, and IL-17, play a central role in the pathogenesis of uveitis." (PMID 39075390, 2024). "Key cytokines associated in uveitis include interleukins (IL), specifically IL-6 and IL-17, tumor necrosis factor alpha (TNF-α), and interferon gamma (IFN-γ), each exhibiting distinct effects on the pathogenesis of uveitis." (PMID 39075390, 2024). "Adalimumab, a recombinant human anti-TNF-α antibody, is utilized in treating JIA and uveitis, among other conditions." (PMID 39062219, 2024). "In the best of our knowledge, we present the first comparative study of three anti-TNF-alpha drugs (ADA, IFX and CZP) in the treatment of patients with CME due to BD uveitis." (PMID 39685848, 2024). "In vitro studies have shown that tumor necrosis factor-alpha (TNF-α), an established cytokine involved in uveitis and mainly expressed by macrophages, promotes hyalocyte proliferation, migration, and gel contraction." (PMID 38568222, 2024). "RvD1 is a ligand for ALXR/FPR2, and its effects have been shown in an endotoxin-induced uveitis rat model where direct IVT administration of RvD1 improved clinical scores and reduced TNF-α and NF-κB activation." (PMID 38396985, 2024). "SOCS1-KIR administration also led to significantly reduced TNFα and IL-10 secretion in PHA-stimulated equine PBMCs, isolated from both non-uveitis and ERU horses." (PMID 39867889, 2024). "In addition, since Golimumab which is one of other TNF inhibitors, and Anakinra and Canakinumab which are Interleukin (IL)-1 Inhibitors, are progressing to be used as new treatments for BD uveitis, it is expected further improving the visual prognosis of BD patients with uveitis." (PMID 36744150, 2023). "IL-6, TNFα, and CXCL10 were found to be significantly elevated in the aqueous humor (AH) of patients with BD uveitis, sarcoidosis, and toxoplasmosis uveitis as compared to non-inflammatory controls." (PMID 37297843, 2023).